DYSF (dysferlin)
Diseases named in the same sentence as DYSF in open-access papers (continued):
Sharing a sentence is not in itself a finding about the gene and the disease.
dysferlinopathy (continued). "Recent advances in the study of dysferlinopathy have highlighted the necessity for the maintenance of calcium handling in altering or slowing the progression of muscular degeneration resulting from the loss of dysferlin." (PMID 24639655, 2014). "Until recently, it was largely thought that this muscle-specific role was related to the membrane repair activity of Dysferlin at the muscle plasma membrane, since a major pathological hallmark of Dysferlinopathies is membrane damage with an accumulation of sub-sarcolemmal membrane vesicles." (PMID 24244862, 2013). "Conversely, to examine whether the recruitment of MG53 requires dysferlin, and to elucidate the molecular pathology of dysferlinopathy, we used skeletal muscle from dysferlin-deficient A/J mice transfected with EGFP-MG53 to perform a membrane repair assay." (PMID 23145354, 2012). "Dysferlinopathies are caused by mutations in the dysferlin gene (DYSF)." (PMID 22194990, 2011). "Dysferlinopathy is a type of muscular dystrophy characterized by mutations in the DYSF gene." (PMID 22194990, 2011). "Hence, we hypothesised that these molecular aspects might be rapidly exacerbated by GC treatment in dysferlinopathy and may manifest as the functional decline of dysferlin-deficient muscles within a short treatment period." (PMID 39123261, 2024). "The Mutation Taster database indicated that c.5628C>A and c.5633A>T of DYSF were predicted to be “disease-causing” mutations that could change amino acid sequences, affect protein features, and may have an effect on splicing, which leads to dysferlinopathy." (PMID 38903757, 2024). "It is important to note that while dysferlin deficiency compromises plasma membrane integrity and disrupts intracellular equilibrium, other elements, such as specific calcium channels, might also be at play in the inflammation associated with dysferlinopathy." (PMID 38540676, 2024). "To study the pathological mechanisms leading to dysferlinopathies and to investigate therapeutic strategies, we created the mouse model Dysf p.Y1159X/p.Y1159X by integrating the nonsense mutation NM_003494.3: c.3477C > A (p.Y1159X) which leads to dysferlin absence." (PMID 37239109, 2023). "DYSF may act in membrane repair predominantly through mini-dysferlin isoforms, which explain why mutations leading genomic deletion in the first exons induce moderate forms of dysferlinopathies." (PMID 34067866, 2021). "Although previous study have identified single heterozygous Dysferlin mutations as pathogenic causes of Dysferlinopathies, the majority of dysferlin variants is required to be homozygous or potentially compound for functional alterations and the incidence for Dysferlinopathies." (PMID 34276779, 2021). "In myocytes developed from induced pluripotent stem cells from a patient carrying p.Trp999Cys mutation, nocodazole treatment increases dysferlin levels and improves membrane resealing, suggesting that dysferlin degradation may be a potential drug target for the treatment of dysferlinopathy." (PMID 33841177, 2021). "Furthermore, dysferlin-deficiency attenuated muscle regeneration resulting in the presence of an increased number of immature fibers and suggesting that regenerative process is delayed or incomplete in dysferlinopathy." (PMID 32106631, 2020). "Targeting TSP-1 may constitute a therapeutic approach in patients carrying mutations affecting proper folding of dysferlin since it would reduce inflammation and avoid the undesirable side-effects reported in patients with dysferlinopathy treated with prednisone." (PMID 33246442, 2020). "Many dysferlin knockout mouse models are available to study the impacts of molecular treatments on dysferlinopathy." (PMID 41584851, 2026). "Among the LGMDR1 (calpainopathy), LGMDR2 (dysferlinopathy) and LGMDR3−6 (sarcoglycanopathy), the degree of latissimus dorsi involvement were correlated to the severity of periscapular and shoulder girdle muscles which was in contrast to our results." (PMID 41575995, 2026).
dysferlinopathy (continued). "Dysferlinopathy (LMGDR2) is one of the autosomal recessive LGMDs, caused by a homozygous or compound heterozygous mutation in the DYSF gene encoding dysferlin, a protein involved in sarcolemma repair." (PMID 41009401, 2025). "Our assessment of a potential therapeutic effect of muscle PGC-1α in dysferlinopathies, leading to an unexpected outcome, has resulted in the discovery of substantial remodeling of muscle metabolism in mice with an ablated dysferlin gene." (PMID 40021220, 2025). "Supporting the relevance of inflammasome activation in dysferlinopathy, previous studies have shown increased levels of NLRP3, ASC, active caspase-1, and mature IL-1β in skeletal muscles from dysferlin-deficient (A/J) mice." (PMID 41155239, 2025). "In particular, one study examined muscle expressing a “nanodysferlin”, designed to be therapeutic, while another examined muscle expressing a small form of dysferlin encountered in a patient with only a mild form of dysferlinopathy." (PMID 41227369, 2025). "Dysferlinopathy is one type of LGMD and is caused by mutations in the DYSF gene (MIM#603009, GenBank NM_003494.2), encoding dysferlin." (PMID 40565111, 2025). "The exact Implications of dysferlin’s interactions with inflammatory/immune cells and proteins are not yet clear; however, there is a strong indication of an immune contribution to the dysferlinopathy pathology." (PMID 38540676, 2024). "The most common subtypes include LGMD2A (Calpainopathy), LGMD2B (Dysferlinopathy), and LGMD2C-2F (Sarcoglycanopathies)." (PMID 39596609, 2024). "Ongoing research, including a study with patient-derived iPSCs showing the effectiveness of nocodazole in increasing dysferlin levels in cells, indicates promising directions for future dysferlinopathy treatments." (PMID 38540676, 2024). "DYSF-mediated membrane repair can become impaired or dysfunctional in genetic disorders known as dysferlinopathy." (PMID 38539162, 2024). "Research into the pathomechanism of dysferlinopathies predominantly focuses on dysferlin’s integral role in membrane repair." (PMID 38540676, 2024). "Dysferlinopathies represent an ideal myopathy to model using hiPSC technology due to the multi‐functional roles of dysferlin, multicellular involvement, mild disease severity in mouse models, and paucity of primary muscle biopsies." (PMID 38887849, 2024). "In cases suspected of having dysferlinopathy either clinically or pathologically, NGS has aided in identifying DYSF variants in 36%." (PMID 38539162, 2024). "Myoblast transplantation, involving the injection of dysferlin-positive cells into muscle tissue, has shown promise in dysferlinopathy research." (PMID 38540676, 2024). "As such, the human LGMD2B myobundle model is expected to complement transgenic mice as a novel preclinical platform for mechanistic studies and therapeutic testing for dysferlinopathies." (PMID 38887849, 2024). "The MYO-SEQ project conducted whole-exome sequencing (WES) on 1001 patients diagnosed with limb-girdle muscle disease or unexplained limb-girdle weakness, identifying pathogenic variants in DYSF, causing LGMD type R2 or dysferlinopathy, in 45 cases (4.5%)." (PMID 38539162, 2024). "In this study, a hiPSC‐derived 3D tissue‐engineered model of LGMD2B skeletal muscle is developed and applied to show that calcium handling abnormalities drive multiple contractile and metabolic deficits in dysferlinopathy." (PMID 38887849, 2024). "Proteins that partner with dysferlin have been reported to have modifier roles in many cases with dysferlinopathies." (PMID 38540676, 2024). "Genetic loss of dysferlin results in limb girdle muscular dystrophy 2B/2R (LGMD2B/2R) and other dysferlinopathies – rare untreatable muscle diseases that lead to permanent loss of ambulation in humans." (PMID 38887849, 2024).
dysferlinopathy (continued). "Although previous studies have primarily focused on exploring the functional role of dysferlin in sarcolemma membrane repair, numerous aspects of dysferlinopathy's pathomechanism remain elusive." (PMID 39350328, 2024). "This study shows that dysferlinopathy and calpainopathy are frequently occurring LGMD-R subtypes in the enrolled population (DYSF-associated LGMD-R2: 69/261 [26.44%] and CAPN3-associated LGMD-R1:61/261 [23.37%])." (PMID 39678382, 2024). "Dysferlin’s expression in monocytes aligns with its skeletal muscle levels across both healthy individuals and dysferlinopathy patients." (PMID 38540676, 2024). "To date, several genetic studies of dysferlinopathies diagnosed as MMD1 or LGMD2B have been reported in Koreans." (PMID 36672942, 2023). "The clinical phenotypes of dysferlinopathy predominantly included Miyoshi myopathy, LGMD2B, and distal myopathy with anterior tibial onset (DMAT)." (PMID 37974208, 2023). "Our objective in the current study was to specifically assess the importance of the calpain cleaved form of dysferlin in membrane repair and development of dysferlinopathy in a mouse model that lacks expression of dysferlin isoforms containing exon 40a." (PMID 36653852, 2023). "For the interpretation of this results, it would be helpful to collect additional dysferlinopathy cases in which the dysferlin was expressed and analyze the intramuscular transcriptome profiles of these patients." (PMID 38125829, 2023). "In dysferlinopathy, the autophagy program has been found to be activated for degradation of mutant dysferlin aggregates." (PMID 38125829, 2023). "FKBP8/38 agonists can reduce fat-induced hyperlipidemia, with hyperlipidemia being a key feature of dysferlinopathy in LGMD2B/LGMDR2." (PMID 36902136, 2023). "We report a case of dysferlinopathy caused by homozygous NM_001130987.2:c.1471dupA(p.M491Nfs*15) in DYSF, a frameshift mutation reported to result in LGMD2B." (PMID 36464789, 2023). "The dysferlinopathies are autosomal recessive muscular dystrophies caused by mutations in the gene DYSF, encoding the protein dysferlin, a 230 kDa transmembrane protein that is highly expressed in skeletal muscle." (PMID 37239109, 2023). "Dysferlinopathies are autosomal recessive muscular dystrophies resulting from defects in DYSF (MIM: 603009), which is located on chromosome 2p13 and encodes the dysferlin protein." (PMID 36464789, 2023). "A diagnosis of dysferlinopathy is made when a patient is shown to have >80% reduction in DYSF protein by western blot and is confirmed by sequencing of the DYSF gene to identify the causative mutation(s)." (PMID 35028538, 2022). "Dysferlinopathy refers to a heterogenous group of autosomal recessive disorders that are caused by mutations in DYSF gene that encodes a skeletal muscle protein, dysferlin." (PMID 36042458, 2022). "These diseases (collectively called dysferlinopathy) are caused by mutations in the DYSF gene, which encodes a large (237 kDa) muscle membrane protein — dysferlin." (PMID 34981776, 2022). "Dysferlinopathy refers to a heterogenous group of autosomal recessive disorders that affect a skeletal muscle protein called dysferlin." (PMID 36042458, 2022). "The detection of dysferlin deficiency in muscle or blood and the identification of DYSF mutations are the main tools for diagnosing dysferlinopathy." (PMID 35725460, 2022). "From a therapeutic perspective, these findings support the need to restore the dysferlin transcript containing the alternative exon 40a in patients with dysferlinopathies." (PMID 34888307, 2021). "Immune response is implicated in the tumorigenesis of pancreatic cancer and dysferlinopathy mediated by dysferlin, a similar protein of MYOF." (PMID 34957301, 2021). "At the clinical level, dysferlinopathies exist in two different forms of muscular dystrophies namely LGMD2B/R2 (LGMD2B; MIM# 253601) and Miyoshi Myopathy (MM; MIM# 254130)." (PMID 34888307, 2021).
dysferlinopathy (continued). "Although EB1089 is 50–200 times more potent than vitamin D3, when added to cultured myotubes from a dysferlinopathy patient it only produces a trend towards an increase in dysferlin expression." (PMID 33246442, 2020). "In peripheral blood monocytes (PBM) and myotubes of dysferlinopathy carriers bearing one mutation in DYSF, dysferlin expression is increased after vitamin D3 treatment." (PMID 33246442, 2020). "Together, these data highlight important heterogeneities between dysferlinopathies and other types of MD, and stresses the need to assess the safety and efficacy of AngII-dependent therapies in the LGMD2B patient population." (PMID 31404091, 2019). "Dysferlinopathy phenotypes include progressive atrophy of limb muscles, elevated serum creatine kinase levels, reduced expression of plasmalemmal dysferlin, and prevalence of immature muscle fibers." (PMID 31861684, 2019). "Our data show that the expression of dysferlin is dramatically reduced in dysferlinopathy-derived myoblasts compared to myoblasts from a healthy subject." (PMID 31861684, 2019). "As compared with immortalized myoblasts obtained from a control subject, dysferlin expression and G-actin incorporation were significantly decreased in myoblasts from dysferlinopathy patients." (PMID 31861684, 2019). "Together, these data show that expression of full-length dysferlin restores annexin A2 distribution in dysferlinopathy myoblasts." (PMID 31861684, 2019). "Together, these data strongly suggest that Ca2+-dependent G-actin incorporation is impaired when dysferlin is reduced, such as in the dysferlinopathy context." (PMID 31861684, 2019). "The Jain Foundation, based in Seattle, USA, is entirely focused on LGMD2B/dysferlinopathy/Miyoshi Myopathy." (PMID 29735511, 2018). "It was recently demonstrated that next generation sequencing (NGS) targeting the coding regions of the DYSF gene enables efficient and accurate genetic diagnosis of dysferlinopathy." (PMID 29879922, 2018). "Another study was able to support a diagnosis of primary dysferlinopathy in symptomatic carriers with findings of abnormal dysferlin gene expression in skeletal muscle and monocytes." (PMID 29879922, 2018). "This was confirmed in myotubes derived from cell lines of human dysferlinopathy patients, as well as in normal myotubes where dysferlin was knocked down." (PMID 27229680, 2016). "Dysferlin was detected in skin fibroblasts from both normal humans and wild-type mice, whereas it was barely detectable in fibroblasts from dysferlinopathy patients (patient 1 and 2)." (PMID 26579332, 2015). "Our demonstration of altered t-tubule structure and the elevated Ca2+-sensitive pathways in dysferlin-null muscle is consistent with reports that both are disrupted in dysferlinopathies." (PMID 24639655, 2014). "In dysferlinopathies, treatment startegies differ, because inflammatory mechanisms are often active in the DYSF mutant muscles." (PMID 24626787, 2014). "Most recently, evidence points to an age-dependent enhancement in oxidative stress in dysferlin-deficient muscle leading us to speculate that a progressive enhancement in oxidative stress may temporally associate with the late onset of muscle pathology seen in dysferlinopathy." (PMID 24600403, 2014). "If a reduction in dysferlin-expression would occur in dysferlinopathy patients, then it would affect patients with residual or partially functional dysferlin protein more than patients without any protein." (PMID 23406536, 2013). "We provide proof of principle that AAV5 mediated delivery of dysferlin is a highly promising strategy for treatment of dysferlinopathies and has far-reaching implications for the therapeutic delivery of other large genes." (PMID 22720081, 2012). "Dysferlin protein is absent or severely reduced in the skeletal muscle of patients with dysferlinopathy and of SJL and A/J mice with mutations in the dysferlin genes." (PMID 23145354, 2012).
dysferlinopathy (continued). "Further study is needed to ascertain the crucial functions that dysferlin performs that are relevant to the onset and progression of dysferlinopathies." (PMID 22666441, 2012). "These experiments are helpful in elucidating the molecular pathology of dysferlinopathy and revealed that MG53 accumulated in the skeletal muscles of dysferlin-deficient mice, which develop progressive muscular dystrophy." (PMID 23145354, 2012). "We performed skeletal muscle WB in 17 dysferlinopathy patients and we found that dysferlin expression was 1.1±4.3%." (PMID 22194990, 2011). "Dysferlin-deficient monocytes from SJL/J mice and dysferlinopathy patients were reported to have increased phagocytic activity and dysferlin deficiency induces an upregulation of inflammasome." (PMID 21798087, 2011). "One such construct restored membrane repair and improved the histology of dysferlin-deficient BlAJ mice, but it did not reverse all the effects of the dysferlinopathy." (PMID 41227369, 2025). "Finally, we validated our finding in BLAJ mice (mice carrying the A/J dysferlin mutation that were backcrossed onto the C57BL/6 background), another commonly used mouse model for dysferlinopathies." (PMID 40021220, 2025). "This new aspect of dysferlin biology, with the implications for the pathology of dysferlinopathies, indicates potential novel therapeutic avenues that could decisively complement existing strategies aimed at restoring membrane repair." (PMID 40021220, 2025). "A few of these patients had only a single heterozygous DYSF mutation but the diagnosis of dysferlinopathy was supported by the lack of dysferlin in muscle." (PMID 40545540, 2025). "Collectively, our results not only shed light on a metabolic function of dysferlin but also imply new therapeutic avenues aimed at promoting mitochondrial function and normalizing muscle glycogen to ameliorate dysferlinopathies, complementing efforts that target membrane repair." (PMID 40021220, 2025). "There is a diverse spectrum of dysferlinopathies that result from deficient or absent dysferlin proteins due to pathogenic variants in the DYSF gene." (PMID 39936969, 2025). "Due to the clinical heterogeneity of dysferlinopathy, identical mutations in the DYSF gene can give rise to different phenotypes, including LGMDR2 and MMD, within the same family or may manifest as overlapping phenotypes in an individual patient." (PMID 40740503, 2025). "Accordingly, mutations in the dysferlin gene cause progressive muscular dystrophies, collectively referred to as dysferlinopathies for which no effective treatment exists." (PMID 40021220, 2025). "Dysferlinopathies represent a phenotypically heterogeneous spectrum of muscular dystrophies with autosomal recessive inheritance, characterized by abnormal amyloid deposition and fragments of dysferlin within skeletal muscle tissues." (PMID 38540676, 2024). "Furthermore, genetic ablation of C3 in dysferlin-deficient mice reduced disease severity, indicating that activation of C3 accelerates muscle damage in dysferlin-null mice and that complement-mediated injury is central to the pathogenesis of dysferlinopathy." (PMID 39123261, 2024). "The mild disease severity in dysferlin‐deficient mice and diverse genotype‐phenotype relationships in LGMD2B patients have prompted the development of new in vitro models for personalized studies of dysferlinopathy." (PMID 38887849, 2024). "It has also been reported that activation of AMPK is important for the membrane repair function of dysferlin, as rescued muscle phenotype in models of dysferlinopathy and enhanced myotube membrane recovery from injury, even when dysferlin levels were unchanged." (PMID 39458505, 2024). "A notable instance involves a patient mutation that produced a quasi-dysferlin, which, restored membrane repair in dysferlin-deficient mice, but did not mitigate the distinctive dysferlinopathy-related muscle pathologies." (PMID 38540676, 2024).